COMT (catechol-O-methyltransferase)
Diseases named in the same sentence as COMT in open-access papers (continued):
Sharing a sentence is not in itself a finding about the gene and the disease.
cancer (continued). "For example, genetic variants within OPRM1 have been associated with the symptom of cancer pain in four articles; and genetic variants within COMT have been associated with cancer pain in three articles." (PMID 26872611, 2016). "Remarkably, genetic variations of COMT affect its activity and are associated to various human disorders from psychiatric diseases to estrogen-induced cancers." (PMID 28066248, 2016). "For the interaction of the CYP1A1&COMT, we observed that TC&HL genotypes had a greater risk for c-cancer (OR = 6.07, p = 0.006) and TT&HL genotypes had a protection effect (OR = 0.24, p < 0.001)." (PMID 26798414, 2016). "This body of work has linked COMT genetic variation with a vast array of conditions, including several neurobehavioral disorders, pain sensitivity, and multiple human cancers." (PMID 24460628, 2014). "Both endogenous estrogen and its catechol metabolites can suppress COMT expression and activity, and has been suggested to be a risk factor for estrogen-associated cancers." (PMID 24040167, 2013). "Epidemiological studies have investigated the association of COMT polymorphism with cancers in hormone-responsive tissues, but the results are inconsistent." (PMID 23785672, 2013). "It is shown that a polymorphism in the COMT gene, Rs4680 (Val158Met), influence pain sensitivity in human experimental pain and the efficacy for morphine in cancer pain treatment." (PMID 19094200, 2008). "It is also interesting to note that COMT is implicated in cancer biology and metastasis, and the allelic directionality is consistent with our results (i.e. here met alleles are risk-associated)." (PMID 18159252, 2007). "Genetic polymorphisms in the COMT gene, which encodes catechol-O-methyltransferase, have also been often investigated, and SNPs in this gene were found to be associated with responsiveness to opioids even in advanced cancer patients." (PMID 36230616, 2022). "Studies like this exploratory analysis suggest that COMT gene variants may be useful in targeting subpopulations with cancer-related fatigue for treatment and symptom management with OLP." (PMID 34267689, 2021). "COMT deficiency or gene polymorphism in COMT is important only in cancer in women." (PMID 32498358, 2020). "Apart from psychiatric disorders, COMT gene polymorphisms were also relevant to cancer risk." (PMID 33282008, 2020). "Patients with OPRM1 A/A genotype and patients with COMT Met/Met genotype have been invariably associated with a more favorable phenotype, also in specific cancer patients’ populations: less pain sensitivity, better response to opioids with lower consumption, less side effects." (PMID 32708424, 2020). "The association between COMT Val158Met polymorphism (rs4680) and the inter-individual differences in the response to opioid analgesic therapy was investigated in a cohort of 87 Italian paediatric patients receiving opioids for cancer pain (STOP Pain study)." (PMID 30704436, 2019). "Furthermore, a systematic review of the association between opioid response in cancer patients and the COMT polymorphism was performed in accordance with the Cochrane Handbook and the Prisma Statement." (PMID 30704436, 2019). "In our sample of paediatric patients, the association with rs4680 COMT polymorphism was found using the total dose requested for maximal possible pain reduction, whereas the 24-h dose that correlated in adult cancer patients only showed a slight tendency towards association." (PMID 30704436, 2019). "This prospective association study investigated seven variations in the OPRM1, OPRK1 and COMT gene, which encode Mu and KAPPA opioid receptors, and Catechol-O-methyltransferase enzyme respectively, in a cohort of 129 Tunisian cancer pain patients under oral morphine treatment." (PMID 29259946, 2017). "Women with COMT LL genotype had a higher risk of developing c-cancer (OR = 4.83, p < 0.001)." (PMID 26798414, 2016).
cancer (continued). "A COMT inhibitor was associated with an increase in kidney tubular adenomas and carcinomas." (PMID 27790617, 2016). "If indeed Met/Met carriers have more flattened DCS during the first months post-diagnosis, it could be that COMT variant is a risk factor in cancer patients." (PMID 26313260, 2015). "COMT polymorphisms have been broadly explored, not only within neurobiology, but also for their role in carcinogenesis, particularly in hormonally distinct cancers of the uterus and breast." (PMID 24460628, 2014). "The role of COMT may be implicated in cancer and neurological and cardiovascular disorders." (PMID 34209963, 2021). "Moreover, increased expression of MAOB mRNA was significantly associated with COMT mRNA in the same cancer tissues (ρ = 0.738; p < 0.001), and increased expression of MAOA mRNA was significantly associated with COMT mRNA in the same cancer tissues (ρ = 0.557; p < 0.001)." (PMID 34209963, 2021). "Present research suggests that the A allele in COMT polymorphism could be a marker of opioid sensitivity in paediatric cancer patients (STOP Pain), as well as in adults (Systematic Review), indicating that the polymorphism impact could be not age-dependent in the cancer pain context." (PMID 30704436, 2019). "Therefore, in a patient cohort in which we have previously shown that the Rs4680 (Val158Met) polymorphism influences the efficacy of morphine for cancer pain, we investigated if variability in other regions in the COMT gene also contribute to interindividual variability in morphine efficacy." (PMID 19094200, 2008). "Isoforms with increased proportions in stem/TA-like cells (cancer cells) were linked to worse survival, such as COMT-202, TTC39A-216; while increased proportions in stem/TA-like cells (cancer) indicated better prognosis, such as STAG2-203 and CCND3-203." (PMID 40702779, 2025). "Clinical trials demonstrate positive results in cancer prevention through supplementing tocopherol and catechol-O-methyltransferase (COMT)." (PMID 38671875, 2024). "A case–control study of the associations between the CYP1B1 and COMT polymorphisms and invasive EC risk revealed that carriers of the CYP1B1 N453S allele had a statistically significant decrease in cancer risk." (PMID 39682707, 2024). "The O-methylation of catechol estrogens by COMT can serve as a protective pathway via the minimization of depurinating DNA adduct formation and cancer prevention." (PMID 39682707, 2024). "In prostate and breast cancer cell lines, overexpression of COMT inhibited cancer progression by limiting cell invasion and enhancing apoptosis." (PMID 38355921, 2024). "Cancer patients who had at least one A allele (OPRM-A118G) and a Met allele (COMT-Val158Met) appeared to have less pain and analgesia, as well as fewer side effects." (PMID 37623452, 2023). "The effects of the G472A (rs4680) SNP in COMT on plasma concentration and dose requirements of morphine were evaluated in a prospective study conducted in 48 Japanese patients with cancer." (PMID 36422103, 2022). "APOE, BDNF, and COMT candidate genes have demonstrated influence on neurocognition in oncology populations, though limited data exists specific to pediatric cancer and CNS tumor populations." (PMID 35814456, 2022). "Significantly strong positive associations were also found between the mRNAs of MAOA, MAOB, and COMT in the same cancer tissues." (PMID 34209963, 2021). "Our study is the first to demonstrate the associations between MAO and COMT in BQ-related OPMD and cancers of the oral cavity and pharynx." (PMID 34209963, 2021). "By expressing COMT protein in cells, we observed reduced migration ability and increased apoptosis of these cancer lines." (PMID 34587154, 2021). "In kidney, both tissues and cell lines have much lower COMT levels in cancer compared to normal counterparts." (PMID 34587154, 2021).
cancer (continued). "Although the COMT SNP rs4680 and rs4818, are well-studied, little is known about their influence on cancer-related fatigue (CrF) and placebo response." (PMID 34267689, 2021). "In other cancers, COMT has also been shown to have a pro-apoptotic effect although the genes involved differ." (PMID 34587154, 2021). "Nevertheless, less attention has been paid to the possible contribution of COMT to the development of cancers." (PMID 34209963, 2021). "For ovary, cancer lines had much lower COMT protein expression compared to ovarian surface epithelial cells." (PMID 34587154, 2021). "Our findings highlight the association of MAO and COMT biomarkers in inducing the risks of OPMD and cancers of the oral cavity and pharynx." (PMID 34209963, 2021). "Entacapone, a selective and reversible inhibitor of catechol-O-methyltransferase, was positively correlated with eight cancer types (BRNCA, CERV, CHLCA, DLBCL, FLYMPH, LIVCA, PACA, and STCA)." (PMID 34203763, 2021). "There are several studies about the effect of COMT SNPs other than rs4680 on pain sensitivity in cancer patients, the response to different analgesics and the susceptibility to schizophrenia and other behavioural disorders." (PMID 32533012, 2020). "Cancer patients with at least one A allele (OPRM – A118G variant) and a Met allele (COMT Val158Met) seem to experience less pain and more analgesia, with less side effect." (PMID 32708424, 2020). "Available information on the impact of genetic variability in COMT on the effect of opioids in cancer pain remains limited, especially in children." (PMID 30704436, 2019). "COMT metabolizes catechol estrogens (i.e., 2-OHE2, 2-OHE1, 4-OHE2, and 4-OHE1) to methyl-estrogen, which has been associated with cancer development and progression." (PMID 31156495, 2019). "Although further studies are needed to confirm these findings, to date these evidences are still not sufficient to support a previous expensive evaluation of COMT SNPs before starting an opioid therapy in children suffering for cancer pain." (PMID 30704436, 2019). "The effect of polymorphisms in the OPRM1 and COMT genes, which transcribe opioid receptor μ 1 and catechol-O-methyltransferase respectively, are relatively well categorized in their effect on acute postoperative, cancer-related and chronic pain." (PMID 31547335, 2019). "To identify a biomarker for selection of opioids for cancer pain relief, we planned a randomized comparative study of morphine and oxycodone using the COMT rs4680 SNP as a biomarker." (PMID 28985716, 2017). "In the present study, seven SNPs were screened in Mu opioid receptor, Kappa opioid receptor and COMT genes for genetic vulnerability to morphine dose requirement in case of cancer pain patients." (PMID 29259946, 2017). "We screened seven SNPs in Mu opioid receptor, Kappa opioid receptor and COMT genes for genetic vulnerability to morphine dose requirement in case of cancer pain patients." (PMID 29259946, 2017). "Methylation by catechol-O-methyltransferase (COMT) enzyme significantly decreased the chemopreventive activity of EGCG in several cancers." (PMID 29301217, 2017). "Our study was the first in Tunisia to investigate the joint effects of polymorphisms in Mu and KAPPA opioid receptors genes and the COMT gene in the clinical efficacy of morphine for cancer patients." (PMID 29259946, 2017). "Combination of EGCG and Tolcapone (TOL) (a COMT inhibitor) was found to improve the bioavailability of EGCG and to synergistically enhance the cancer suppressive effect of EGCG by inhibiting the COMT-mediated methylation of EGCG in vivo." (PMID 27483305, 2016). "The CYP1A1 TT and COMT LL genotypes had higher estradiol levels in c-cancer (p < 0.001 and p = 0.037, resp)." (PMID 26798414, 2016). "The present study is the first to undertake a longitudinal analysis of goal disturbance and cortisol levels in cancer patients, and the moderating role of COMT." (PMID 26313260, 2015).
cancer (continued). "The COMT enzyme effects the degradation of both catecholamines and catecholestrogens (important intermediary metabolites in estrogen induced cancers), by the addition of a methyl group." (PMID 24460628, 2014). "The rationale for studying the influence of COMT on hormonally influenced cancer relates to the role of COMT on catecholamines and in estrogen metabolism." (PMID 24460628, 2014). "According to systematic review of the literature, low COMT activity enhances opioid analgesia and adverse effects in some cancer pains via increasing the absolute amount of opioid receptors." (PMID 23766564, 2013). "Effects of COMT Val/Met in cancer biology have almost always been discussed in the context of its role in detoxifying carcinogens and estrogens." (PMID 20520724, 2010). "This implies that estrogen-related mechanisms may affect the two cancers differently, although some genomic regions, including COMT, ESR1, and UGT1A1, impact both the risks of female DGC and OvC." (PMID 39862296, 2025). "Few studies have investigated the potential role of COMT in cancer management." (PMID 40490448, 2025). "In addition, 2-methoxyestradiol, a product of COMT catabolism of 2-hydroxyestradiol, inhibits cancer progression, suggesting COMT plays a suppressive role in cancer." (PMID 38355921, 2024). "Therefore, this study aims to delineate the association between SCZ-related genes (HTR2A, COMT, PRODH) and different cancers." (PMID 37564635, 2023). "Questions for further research included whether the pharmacogenetic effect of vitamin E and COMT on cancer prevention extends to dietary vitamin E intake and to specific cancer types." (PMID 37974041, 2023). "SCZ-associated genes (HTR2A, COMT, and PRODH) were subjected to pan-cancer analysis." (PMID 37564635, 2023). "The reduced levels of SAM (on account of increased flux through COMT catalyzed reaction in the CRC–microbe model) can result in increased cancer cell proliferation and growth making COMT a promising drug target, an aspect that can motivate future experimental studies." (PMID 35046399, 2022). "The COMT gene is thus shown to play a suppressive role in cancer." (PMID 34587154, 2021). "These pro-apoptotic and anti-proliferative effects of COMT could therefore contribute to reducing cancer cell growth." (PMID 34587154, 2021). "In this study, we examined whether genetic variation in COMT, at the functional SNP rs4680 and linked rs4818, influenced open-label placebo (OLP) responses found in cancer survivors reporting moderate to severe CrF." (PMID 34267689, 2021). "The COMT rs4818 findings replicated findings in a similar study of OLP in cancer fatigue." (PMID 34267689, 2021). "Variants of thiopurine S-methyltransferase TPMT (rs12201199, rs180046 and rs1142345) and catechol O-methyltransferase (COMT) (rs4646316 and rs9332377) were reported to be associated with ototoxicity after treatment with cisplatin in different cancers, including HGOS." (PMID 32629971, 2020). "This lower activity of COMT enzyme, with a consequent increase of dopamine bioavailability, was reported to increase opioid receptor density and to enhance opioid analgesia and adverse effects in several types of cancer pain." (PMID 30704436, 2019). "Patients who are treated for cancer-related pain may experience opioid-related side effects if they possess a genetic variation in COMT." (PMID 31547335, 2019). "A biomarker for selection of opioids for cancer pain relief would be particularly useful clinically, and therefore we have planned a randomized comparative study of morphine and oxycodone, using the COMT rs4680 SNP as a biomarker." (PMID 28985716, 2017). "In conclusion, the present study is the first to show that goal disturbance after cancer diagnosis may lead to increased cortisol awakening responses on the long term, but that this effect is less pronounced for patients with the Met/Met COMT genotype." (PMID 26313260, 2015).
cancer (continued). "Human studies have suggested that high levels of CYP1B1 expression and low levels of COMT expression in adjacent non-tumour tissue were associated with an increased risk of BC and other E2-responsive cancers." (PMID 24629213, 2014). "This study suggest that genetic variability in the COMT gene influence the efficacy of morphine in cancer pain patients, and that increased understanding of this variability is reached by expanding from analyses of single SNPs to haplotype constructions and analyses." (PMID 19094200, 2008). "This study suggests that genetic variability in the COMT gene influence the efficacy of morphine in cancer patients with pain, and that increased understanding of this variability is reached by expanding from analyses of single SNPs to haplotype construction and analyses." (PMID 19094200, 2008). "We have identified a frequent haplotype (haplotype 1) in the COMT gene that may influence the morphine dose requirements in cancer patients with pain." (PMID 19094200, 2008). "This suggests that COMT may play a role in cancer therapy by influencing immune mechanisms." (PMID 40299330, 2025). "Further, COMT breaks down catechol estrogens which can be genotoxic and may contribute to cancer." (PMID 38355921, 2024). "Moreover, catechol-o-methyltransferase (COMT) Val158Met polymorphism (rs4680) is involved in pain modulation, which has been evidenced to influence opioid use in pediatric patients with cancer and adult patients with chronic noncancer pain." (PMID 36556242, 2022). "In addition, epidemiology studies will continue to determine whether genetic risk factors for neurodegenerative diseases, for example, variations in apolipoprotein E (APOE) or COMT, can predict risks of developing chemobrain in cancer survivors." (PMID 32346964, 2020). "Totally 8 SNPs in 3 genes, COMT, HTR3B, CHRM3 (rs1176744, rs3782025, rs1672717, rs165722, rs4680, rs4633, rs10802789, rs685550), were significantly associated with the interindividual differences in nausea and vomiting among cancer patients treated with opioids." (PMID 23766564, 2013). "Endogenous COMT activity is a major determinant in facilitating estrogen metabolism, and it plays an important role in the pathophysiology of different human disorders including Parkinson’s disease, depression, schizophrenia, hypertension, and various estrogen-induced cancers." (PMID 24040167, 2013). "TIMER database was used for pan‐cancer analysis of different pain genes (Nav1, EHMT2, SP1, SLC6A4, COMT, OPRM1, OPRD1, CYP2D6, and CYP3A4)." (PMID 38352696, 2024). "Although associations have been identified between IL-4, IL-6, IL-8, IL-10, IL-1β, TNF-α, COMT, CLOCK, PER, and 5-HTTLPR-related genes and cancer-related fatigue, the relationship between IL-6 and cancer-related fatigue remains controversial." (PMID 39372868, 2024). "In 39 cancer types, including GBMLGG, HTR2A, COMT, and PRODH expressions were significantly correlated with immune cell infiltration." (PMID 37564635, 2023). "This study explored the expression of SCZ-related genes (HTR2A, COMT, and PRODH) in pan-cancer analysis." (PMID 37564635, 2023). "The correlation between TMB and HTR2A, COMT, and PRODH was examined for each cancer using Spearman’s correlation method." (PMID 37564635, 2023). "A possible explanation for this inconsistency is the interactive effect of the catechol-O-methyltransferase (COMT) gene and supplemental vitamin E on cancer." (PMID 37974041, 2023). "Both COMT rs4680 high-activity G-allele and rs4818 C/G genotype were significantly associated with decreased fatigue severity and improved fatigue-distressed quality of life among cancer survivors participating in a trial of the non-deceptive administration of placebo pills." (PMID 34267689, 2021). "Non-cancer therapy consisted of ondansetron (CYP2D6—CPIC Level A) for nausea, as well as morphine (OPRM1, COMT—CPIC level C) and tramadol (CYP2D6—CPIC Level A, FDA Tier 1; OPRM1, COMT—CPIC level C) for pain management." (PMID 33799547, 2021).